GRN (granulin precursor)
Diseases named in the same sentence as GRN in open-access papers (continued):
Sharing a sentence is not in itself a finding about the gene and the disease.
glioma (14 papers, 2018 to 2026). A benign or malignant brain and spinal cord tumor that arises from glial cells (astrocytes, oligodendrocytes, ependymal cells). "GRN is a known glioma-associated growth factor, its overexpression in GBM tumours and prognostic significance is well established." (PMID 38212481, 2024). "For example, GRN expression is significantly up-regulated in glioma cells, which is associated with the poor prognosis of patients; GRN expression is raised in HCC tissues, which is related to larger tumor size, venous infiltration and early intrahepatic recurrence after the surgery." (PMID 34002672, 2021). "A TCGA analysis found GRN as a prognostic biomarker in glioma which might be related to immune infiltration." (PMID 40736401, 2025). "We found that the GRN mRNA expression level correlates with glioma patients’ tumor grade." (PMID 37091137, 2023). "Myeloid/microglial cells can communicate with MAN1C1-expressing glioma cells via signals produced (SPP1, GRN, PSAP, HBEGF, LGALS9, WNT5A)." (PMID 39333557, 2024). "GRN has emerged as a key prognostic marker for overall survival (OS) and disease-free survival (DFS) in patients with lower-grade glioma (LGG) and GBM." (PMID 37091137, 2023). "Furthermore, other cells within the GRN and PSAP signaling pathways were regulated by glioma cells, M1 macrophages, M2 macrophages, and endothelial cells." (PMID 38824202, 2024).
cognitive decline (13 papers, 2018 to 2025). "Converters with a MAPT and GRN mutation had mutual as well as gene-specific profiles of cognitive decline." (PMID 29627938, 2018). "GRN mutation carriers also display a substantial global cognitive decline, with lower MMSE and Frontal Assessment Battery (FAB) scores (n = 4); the Wisconsin Card Sorting Test (WCST) (n = 3) is particularly sensitive to executive dysfunction in these individuals." (PMID 40649976, 2025). "Cognitive decline in language, and attention and mental processing speed was already present in the presymptomatic stage of C9orf72 mutation carriers, and in executive function in GRN mutation carriers, albeit to a lesser extent than in the symptomatic stage." (PMID 39500348, 2024). "In addition, MAPT mutation carriers are known for their rapid cognitive decline once they become symptomatic, probably causing lower performance on neuropsychological tests compared to patients with a GRN or C9orf72 mutation in their early symptomatic stages." (PMID 39229325, 2024). "M26 was elevated prior to symptom onset and predicted cognitive decline in GRN carriers, highlighting the early stage prognostic utility of spliceosomal proteins in genetic FTLD-TDP." (PMID 38585969, 2024). "We compared cognitive profiles cross-sectional in patients with bvFTD due to mutations in GRN, MAPT or C9orf72 and report patterns of cognitive decline in a subset of patients with follow-up data." (PMID 32052166, 2020). "The similar patterns of cognitive decline in bvFTD as MAPT, and nfvPPA as GRN are related to the dominant genotype in each group (e.g. all nfvPPA converters have a GRN mutation)." (PMID 29627938, 2018).
atherosclerosis (12 papers, 2015 to 2025). A disease characterized by the build-up of fatty material and calcium deposition in the arterial wall resulting in partial or complete occlusion of the arterial lumen. "GRN has previously been implicated in atherosclerosis progression and incident MI39." (PMID 30111768, 2018).
neuroblastoma (12 papers, 2011 to 2024). Neuroblastoma (NB) is the most common solid, extracranial childhood tumor. "Although the levels of PLAT and GRN expression are inversely correlated with neuroblastoma patient survival, PLAT has a complex role in cancer progression." (PMID 38495925, 2024). "Our results showed that PGRN deficiency induced mitochondrial depolarization, increased ROS production and lowered ATP levels in GRN KD SH-SY5Y neuroblastoma cells." (PMID 36978829, 2023). "Since the submission of our work, another group have demonstrated GRN readthrough in response to G418 in a mouse neuroblastoma cell line (N2A) overexpressing a human GRN R493X construct." (PMID 32178712, 2020). "Recently, this technique was employed to show the physical binding between miR-659-3p and progranulin (GRN) mRNA in neuroblastoma cell lines." (PMID 28125734, 2017). "Finally, we found that trehalose increased GRN mRNA in a dose-dependent manner in H4 cells and human neuroblastoma cells using quantitative real-time PCR (qPCR)." (PMID 27341800, 2016). "Furthermore, previous results from our lab showed that PGRN insufficiency regulated the intrinsic/mitochondrial apoptosis pathway in GRN knockdown (KD) SH-SY5Y neuroblastoma cells and peripheral cells from FTLD-TDP patients carrying a LOF GRN mutation (c.709-1G > A)." (PMID 36978829, 2023). "PTX3 and PLAT are critically involved in sEV-induced neuroblastoma metastasis, while GRN plays no significant role." (PMID 38495925, 2024). "We found that GRN-2,3 could be detected at steady-state levels in all human cell lines tested, notably with the highest levels in H4 (neuroglioma) and SH-SY5Y (neuroblastoma) cell lines." (PMID 28828399, 2017).
COVID-19 (11 papers, 2021 to 2026). A disease caused by infection with severe acute respiratory syndrome coronavirus 2. "Specifically, IFN, TNF and NF-kB pathways, cytokine SPP1, GRN, the receptor tyrosine kinase AXL [TE85], NLR and RIG-I signaling are strongly altered by SARS-CoV-2 [TE76], contributing to severe forms of COVID-19." (PMID 34876157, 2021).
schizophrenia (10 papers, 2012 to 2026). A major psychotic disorder characterized by abnormalities in the perception or expression of reality. "Among these, an association with 17q21, the locus containing GRN, has been shown in Latino populations with schizophrenia and in patients with BPD." (PMID 22505994, 2012). "In three mixed families, a causal GRN mutation was found, even in family members diagnosed with schizophrenia." (PMID 22505994, 2012). "Furthermore, loss-of-function GRN mutation was found in two siblings diagnosed as schizophrenia and FTD, respectively, and GRN SNPs have been linked to risk of schizophrenia." (PMID 36233357, 2022). "The previous studies have confirmed the association between the GRN mutations and schizophrenia." (PMID 35964197, 2022). "In conclusion, GRN variability decreases the risk to develop BPD and schizophrenia, and progranulin plasma levels are significantly lower in BPD patients than in controls." (PMID 22505994, 2012). "In conclusion, we demonstrated that GRN variability contributes to schizophrenia and BPD development and that progranulin plasma levels are lower in patients with BPD than in controls, although this findings need a replication in a larger cohort." (PMID 22505994, 2012). "GRN is localized in a region of chromosome 17q21 previously shown to be associated with BPD and schizophrenia." (PMID 22505994, 2012). "Closer examination revealed progranulin (GRN) as a potential marker of schizophrenia." (PMID 36747015, 2023). "The UBQLN2 P500S and the TBK1 R271W/GRN T220I carriers have a family history of schizophrenia." (PMID 35964197, 2022). "Additionally, reduced GRN expression impairs synaptic plasticity and long-term potentiation (LTP); therefore, GRN deficits may be related to the pathophysiology of schizophrenia and autism." (PMID 41169352, 2025).
progressive supranuclear palsy (9 papers, 2019 to 2025). A rare late-onset neurodegenerative disease characterized by supranuclear gaze palsy, postural instability, progressive rigidity, and mild dementia. "In contrast to MAPT, Richardson syndrome is rarely seen in cases with GRN mutations." (PMID 40722695, 2025). "We identified one novel missense GRN mutation (c.1498G>A, p.V500I) in this patient, who initially presented typical behavioral-variant frontotemporal dementia (bvFTD) features but then presented progressive supranuclear palsy (PSP) clinical characteristics 5 years after onset." (PMID 34631218, 2021).
psoriasis (9 papers, 2013 to 2025). An autoimmune condition characterized by red, well-delineated plaques with silvery scales that are usually on the extensor surfaces and scalp. "The results revealed that the outgoing signals of CD70, GRN, ncWNT, and GAS from DCs were significantly increased in psoriasis." (PMID 38596682, 2024).
cortical atrophy (8 papers, 2010 to 2025). "Our analysis revealed distinct sets of PLS1 genes positively or negatively associated with cortical atrophy for C9orf72-bvFTD, GRN-bvFTD, and MAPT-bvFTD, potentially reflecting molecular mechanisms underlying neuroanatomical changes." (PMID 39920674, 2025). "In a case of bvFTD due to GRN mutation reported by Tsai and coworkers, [18F]flortaucipir binding was elevated compared with that in controls in expected areas and mirrored cortical atrophy on MRI." (PMID 36513817, 2023). "The GRN mutation carrier also showed asymmetric tracer binding, corresponding to asymmetric cortical atrophy." (PMID 30704514, 2019). "In this study, 22% of patients diagnosed with LPA (2/9) were found to have GRN mutations, which have been shown previously to be associated with asymmetrical hemispheric cortical atrophy frequently involving the parietal lobe." (PMID 19679189, 2010). "Similarly, within the genes associated with cortical atrophy in GRN-bvFTD, there were genes connecting to “neurotransmission and synaptic signaling”." (PMID 39920674, 2025). "Still, the proposed role for GRN across FTLD in conjunction with an appearance of asymmetric cortical atrophy specific to the mutation carriers has provided a strong argument to determine regulatory mechanisms, including epigenetic mechanisms, influencing GRN expression." (PMID 39975316, 2025). "Asymmetric cortical atrophy was found early, 5 years before expected symptom onset in asymptomatic GRN mutation carriers, while the underlying pathological cause for the asymmetry remains unclear." (PMID 32184751, 2020). "In addition, investigations in different time windows during the disease course may capture the variable findings in the laterality of lobar cortical atrophy across individuals with GRN mutations." (PMID 32184751, 2020). "Shared genes with positive weights in C9orf72-bvFTD also displayed positive weights in GRN-bvFTD, indicating their common expression in regions more spared from cortical atrophy." (PMID 39920674, 2025). "By mapping different neurotransmitter systems to cortical structure, the involvement in GRN-bvFTD spans multiple neurotransmitter systems, thereby reinforcing the role of various neurotransmitter pathways in cortical atrophy in GRN-bvFTD." (PMID 39920674, 2025).
liver cancer (8 papers, 2009 to 2024). An epithelial or non-epithelial malignant neoplasm that arises from the liver. "It is found that increased gene copy number variations (CNVs) contributed to the overexpression of granulin precursor (GEP) in a subset of liver cancer." (PMID 38374893, 2024). "This study provides evidence that the combination of GRN A and cisplatin is able to sensitize the liver cancer to cisplatin, and that targeting ENO1 is a promising approach for enhancing the antitumor activity of cisplatin." (PMID 30301274, 2018).
memory impairment (8 papers, 2013 to 2025). "Overall, patients with GRN mutations present a cognitive–behavioural profile characterised by severe memory impairment, alongside moderate difficulties in other domains." (PMID 40649976, 2025). "Early memory impairment suggestive of AD is also observed amongst GRN mutation carriers, sometimes in association with motor disorders." (PMID 23338750, 2013).
Gaucher disease (7 papers, 2019 to 2025). Gaucher disease (GD) is a lysosomal storage disorder encompassing three main forms (types 1, 2 and 3), a fetal form and a variant with cardiac involvement (Gaucher disease - ophthalmoplegia - cardiovascular calcification or Gaucher-like disease). "In addition to AD and PD/LBD, GRN variation has also been implicated in Gaucher disease, FTLD-TDP and/or motor neuron disease with C9orf72 repeat expansions, ALS, and limbic-predominant age-related TDP-43 encephalopathy neuropathological change (LATE-NC)." (PMID 40713630, 2025).
ischemia (7 papers, 2015 to 2024). A hypoperfusion of the BLOOD through an organ or tissue caused by a PATHOLOGIC CONSTRICTION or obstruction of its BLOOD VESSELS, or an absence of BLOOD CIRCULATION. "Neutrophiles are infiltrated in brain parenchyma after ischemia stroke and the increased activity of neutrophil elastase cleaves PGRN into GRN peptide, exacerbating the inflammation and tissue damage after ischemia." (PMID 38166912, 2024).
multiple sclerosis (7 papers, 2013 to 2022). A progressive autoimmune disorder affecting the central nervous system resulting in demyelination. "Although downregulating TREM2 expression or reducing CSF sTREM2 levels could be a therapeutic target for individuals with FTD secondary to GRN mutations, animal models of multiple sclerosis deteriorated with TREM2 inhibition." (PMID 30111356, 2018). "GRN is found to be up-regulated in neurodegenerative diseases such as AD and multiple sclerosis and may also function in neuro-inflammation." (PMID 32545722, 2020).
osteoarthritis (7 papers, 2017 to 2025). A noninflammatory degenerative joint disease occurring chiefly in older persons, characterized by degeneration of the articular cartilage, hypertrophy of bone at the margins and changes in the synovial membrane. "Later studies confirmed GRN as a ligand of TNFR, implicating GRN in many inflammatory diseases (e.g., contact dermatitis, osteoarthritis, colitis, etc.)." (PMID 34366786, 2021).
viral infection (7 papers, 2014 to 2026). "Genetic analysis identified copy number variations (CNVs) in the APP, PSEN1, PSEN2, MAPT, and GRN genes, while viral infections (HSV-1, HSV-2, CMV, EBV, HIV, SARS-CoV-2, Hepatitis A, B, and C) and vitamin D, B12, and B9 deficiencies were measured." (PMID 40725212, 2025). "Lower cognitive performance was associated with CNVs in PSEN1 (exons 1, 9, 12), GRN (exons 1, 6, 12), and MAPT (exons 2, 8), along with viral infections (HSV-1, HSV-2, HAV-2)." (PMID 40725212, 2025).
Anxiety (6 papers, 2010 to 2025). Intense feelings of nervousness, tension, or panic often arise in response to interpersonal stresses. "In mice, GRN knock-out has been shown to produce sex-specific deficits in anxiety-like behavior, motor coordination, and hippocampal synaptic plasticity." (PMID 37863893, 2023). "In GRN carriers, depression and anxiety were predominant in both early and late phases of disease, whereas hallucinations and delusions were not common." (PMID 33404617, 2021). "Most behavioral and neuropsychiatric symptoms increased in the early-intermediate phases and plateaued in the late stages of disease, except for depression, which steadily declined in C9orf72 carriers, and depression and anxiety, which surged only in the late stages in GRN carriers." (PMID 33404617, 2021).
Apathy (6 papers, 2017 to 2023). Apathy is a quantitative reduction of interest, motivation and the initiation and persistence of goal-directed behavior, where often the accompanying emotions, thoughts, and social interactions are also diminished. "Apathy was the most common behavioural symptom in both GRN-NFV and GRN-NOS, consistent with prior reports of this being a frequent feature in people with GRN mutations." (PMID 36938528, 2023). "It is important to remark that apathy, depression or anhedonia have been also found in other FTD murine models, for example those based on overexpression of mutant Tau (also under the CaMKIIα promoter) or in GRN-deficient mice that show cytosolic TDP-43 aggregates." (PMID 37149645, 2023).
autism (6 papers, 2012 to 2025). Persistent deficits in social interaction and communication and interaction as well as a markedly restricted repertoire of activity and interest as well as repetitive patterns of behavior. "Interestingly, while most neurodegeneration-related risk genes, such as APP and SOD1, are usually associated with a specific disease, GRN mutations and polymorphisms appear to be involved in a diverse group of neurological conditions, ranging from FTLD to ALS, AD, PD and even autism." (PMID 36009452, 2022).
colitis (6 papers, 2015 to 2025). Inflammation of the colon. "Several of the significantly co-occurring LR pairs were previously implicated in colitis, and are mostly involved in epithelial integrity and repair (DDR1-CDH1, DSG2-DSC2), immune recruitment (MIF-CD74), and TNF signaling (GRN-TNFRSF1A)." (PMID 38225383, 2024).
gastric cancer (6 papers, 2017 to 2025). A primary or metastatic malignant neoplasm involving the stomach. "In conclusion, CTHRC1 expression may induce tumor associated macrophage infiltration though GRN/TNFRSF1A and AnxA1/FPR1 pathways and also tumor angiogenesis in gastric cancer." (PMID 35928443, 2022). "In addition, CTHRC1 expression may induce tumor associated macrophage infiltration though GRN/TNFRSF1A and AnxA1/FPR1 pathways and also tumor angiogenesis in gastric cancer." (PMID 35928443, 2022).
Aphasia (5 papers, 2010 to 2025). An acquired language impairment of some or all of the abilities to produce or comprehend speech and to read or write. "Regarding the clinical phenotype, patients with CBS and GRN mutations display visuospatial impairment, behavioral changes, aphasia, and/or language deficits." (PMID 40722695, 2025). "Beyond demonstrating a molecular and anatomical association, aphasia associated with GRN mutations suggests a pathophysiological mechanism that may underpin certain key features of the LPA syndrome." (PMID 19766663, 2010). "In addition we identified an additional 2 patients with a cognitive syndrome compatible with Granulin-associated aphasia (mean age 61 ± 14.1 years; 1 female; disease duration 2.8 ± 1.8 years) and were subsequently confirmed to have a proganulin (GRN) mutation (both exon 2 c31fs)." (PMID 23312804, 2013). "A significant association was found between the presence of GRN mutations and specific clinical manifestations shared with FTD, including visuospatial impairment, behavioral changes, aphasia, and language alterations." (PMID 33467748, 2021). "In patients with ALS, TDP-43 lesion allocations are common because it is associated with a pure FTD phenotype or behavior, related to non-fluent aphasia, or linked to the GRN or C9orf72 mutation." (PMID 36226077, 2022).
Autoimmunity (5 papers, 2014 to 2023). The occurrence of an immune reaction against the organism's own cells or tissues. "In one study, patients with semantic FTD or with GRN mutations had the highest prevalence of autoimmunity and exhibited increased levels of TNFα, representing a unique pattern of systemic inflammation." (PMID 34360544, 2021).
breast tumor (5 papers, 2012 to 2024). "GRN was positively correlated with an average of 42.9% of genes in STAT3 signatures but with an average of only 13.5% of genes in MYC signatures, supporting the preferential association of GRN expression with signatures indicative of functional STAT3 activation in primary breast tumors." (PMID 26000098, 2015). "Given previous reports identifying GRN upregulation in breast tumor-instigating cells, we next examined the effects of extracellular GRN on STAT3 function in breast cancer cells." (PMID 26000098, 2015).
depression (5 papers, 2010 to 2023). "Notably, FTD patients with a GRN variant and PGRN-deficient mice have been reported to display depression-like behaviors, indicating that PGRN may be involved in the development of depression." (PMID 36581897, 2022).
ischemic heart disease (5 papers, 2021 to 2025). "GRN was also found in positive associations with three cardiovascular diseases (coronary heart disease (CHD), myocardial infarction, and angina) and negative associations with two biological traits (heel bone mineral density (BMD) and height)." (PMID 36510323, 2022).